SNORD113-5 (small nucleolar RNA, C/D box 113-5)
Synonyms: 14q(I-5)
Gene: Small nucleolar RNA gene on chromosome 14 (100,938,187 to 100,938,264, forward strand). Ensembl gene ENSG00000272474.
Gene Ontology:
Biological process: RNA processing
Cellular component: nucleolus
Homologues: Orthologues: macaque SNORD113-5 (100% identical), chimpanzee SNORD113-5 (99% identical), pig SNORD113-5 (82% identical). Paralogues in human: SNORD113-7 (77% identical), SNORD113-3 (74% identical), SNORD113-8 (74% identical), SNORD113-6 (73% identical), SNORD113-4 (71% identical), SNORD113-9 (71% identical), SNORD114-20 (69% identical), SNORD114-15 (64% identical), SNORD114-21 (64% identical), SNORD114-22 (64% identical), SNORD114-23 (64% identical), SNORD114-24 (64% identical), and 26 more.